ARFGAP1 (ARF GTPase activating protein 1)
Description:
GTPase-activating protein (GAP) for the ADP ribosylation factor 1 (ARF1). Involved in membrane trafficking and /or vesicle transport. Promotes hydrolysis of the ARF1-bound GTP and thus, is required for the dissociation of coat proteins from Golgi-derived membranes and vesicles, a prerequisite for vesicle's fusion with target compartment. Probably regulates ARF1-mediated transport via its interaction with the KDELR proteins and TMED2. Overexpression induces the redistribution of the entire Golgi complex to the endoplasmic reticulum, as when ARF1 is deactivated. Its activity is stimulated by phosphoinosides and inhibited by phosphatidylcholine (By similarity).
Synonyms: ARF1GAP; FLJ10767; bA261N11.3; HRIHFB2281
Tractability: Small molecule: a structure with a bound ligand is known. PROTAC: ubiquitination databases record sites on it; its protein half-life has been measured; a small molecule that binds it is known.
Gene: Protein-coding gene on chromosome 20 (63,272,785 to 63,289,790, forward strand). Ensembl gene ENSG00000101199.
Subcellular location: Cytoplasm; Golgi apparatus
Subcellular location (Human Protein Atlas): Golgi apparatus; Cytosol; Nuclear membrane; Primary cilium; Vesicles
Pathways (Reactome):
Vesicle-mediated transport: COPI-dependent Golgi-to-ER retrograde traffic; COPI-mediated anterograde transport; Clathrin-mediated endocytosis
Cellular responses to stimuli: XBP1(S) activates chaperone genes
Gene Ontology:
Molecular function: GTPase activator activity; protein binding
Biological process: regulation of ARF protein signal transduction; regulation of endocytosis
Cellular component: synapse; cytosol; Golgi membrane; cytoplasm; Golgi apparatus
Genetic constraint (gnomAD): Loss-of-function variants: 25 observed, 55.24 expected, observed/expected ratio (o/e) 0.45, 90% interval 0.33 to 0.63. The upper end of that interval is the gene's LOEUF score, 0.63, which puts it in group 2 of 6, group 1 being the genes least tolerant of losing a copy. Missense variants: 505 observed, 524.44 expected, observed/expected ratio (o/e) 0.96, 90% interval 0.89 to 1.04. Synonymous variants: 238 observed, 209.7 expected, observed/expected ratio (o/e) 1.13, 90% interval 1.02 to 1.26.
Homologues: Orthologues: chimpanzee ARFGAP1 (98% identical), macaque ARFGAP1 (96% identical), guinea pig ARFGAP1 (87% identical), mouse Arfgap1 (87% identical), dog ARFGAP1 (85% identical), rabbit ARFGAP1 (83% identical), pig ARFGAP1 (83% identical), tropical clawed frog arfgap1 (72% identical), zebrafish arfgap1 (58% identical), Caenorhabditis elegans K02B12.7 (42% identical), Drosophila melanogaster ArfGAP1 (40% identical). Paralogues in human: ARFGAP3 (28% identical), ARFGAP2 (25% identical), ARAP1 (17% identical), ASAP2 (17% identical), ARAP2 (16% identical), ASAP1 (16% identical), ASAP3 (16% identical), ARAP3 (15% identical), ACAP2 (14% identical), ACAP3 (14% identical), ACAP1 (14% identical), AGAP2 (14% identical), and 16 more.
Diseases named in the same sentence as ARFGAP1 in open-access papers:
ARFGAP1 is named in the same sentence as 15 diseases in open-access papers, as found by Europe PMC text mining. Sharing a sentence is not in itself a finding about the gene and the disease. The quoted sentences say what the papers report.
Parkinson disease (3 papers, 2012 to 2016). A progressive degenerative disorder of the central nervous system characterized by loss of dopamine producing neurons in the substantia nigra and the presence of Lewy bodies in the substantia nigra and locus coeruleus. "Silencing ArfGAP1 expression was shown to protect against mutant LRRK2 induced neurite shortening, suggesting that ArfGAP1 might also be a potential target in the Parkinson’s disease." (PMID 24926233, 2014).
breast carcinoma (2 papers, 2017 to 2025). "QS11, an ARFGAP1 inhibitor, enhances Wnt/β-catenin signaling by affecting protein trafficking and inhibits migration of ARFGAP-overexpressing breast cancer cells." (PMID 40539058, 2025).
hepatoma (1 paper, 2014). "Our study shows that ARFGAP1 associates transiently with lipid droplets in cultured hepatoma cells (HepG2 and McA-RH7777) upon addition of oleate and at steady state on lipid droplets of some but not all hepatocytes of human liver." (PMID 25397679, 2014).
pancreatic cancer (1 paper, 2025). "The ADP ribosylation factor GTPase-activating protein 1 (ARFGAP1) has been reported to inhibit cell growth through mTORC1 signaling and is a prognostic factor of overall survival in pancreatic cancer patients." (PMID 40429863, 2025).
retina degeneration (1 paper, 2023). "Similarly, we observed a considerable exacerbation of retina degeneration in flies expressing C9orf72 DPRs associated with ArfGAP-1 or ERGIC-53 downregulation." (PMID 37566088, 2023). "A relevant worsening of retina degeneration due to the downregulation of ArfGAP-1 or ERGIC-53 in flies expressing 36 repeats of DPR PR was evidenced." (PMID 37566088, 2023).
steatosis (1 paper, 2014). Increased lipid within the cytoplasm of cells. "As these livers all have varying degrees of steatosis, it will be of interest in the future to determine whether ARFGAP1 localization to lipid droplets correlates with certain pathophysiological states." (PMID 25397679, 2014).
cancer (2 papers, 2020 to 2022). A tumor composed of atypical neoplastic, often pleomorphic cells that invade other tissues. "Recently, it was described that ARFGAP1 might act as a critical regulator of mechanistic target of rapamycin complex 1 (mTORC1) by inhibiting lysosomal localization and activation of mTORC1, resulting in decreased cell growth; therefore, these results propose its potential for cancer therapy." (PMID 35563422, 2022).
infection (1 paper, 2019). The state of being infected such as from the introduction of a foreign agent such as serum, vaccine, antigenic substance or organism. "The EV-A71 VP1 protein was decreased when ARFGAP1 was knocked down by two siRNA 3 days before EV-A71 infection." (PMID 31001221, 2019).
ARFGAP1 also shares sentences with these, for which no sentence is quoted: cardiovascular diseases (1 paper); colorectal cancer (1); dementia (1); lymphoma (1); neuromuscular disease (1); sarcoidosis (1); tumor (1).